EGFR (epidermal growth factor receptor)
Diseases named in the same sentence as EGFR in open-access papers (continued):
Sharing a sentence is not in itself a finding about the gene and the disease.
cancer (continued). "On the other hand, both the EGFR targeting therapy and immunotherapy demonstrate favorable results in preclinical models but fail in clinical trials, suggesting that mice still have significant limitations in modeling human cancer and immunity." (PMID 37601668, 2023). "EGFR signaling modulates cancer cell proliferation through several metabolic processes." (PMID 37601068, 2023). "EGFR/JAK2/STAT5b is also included in PD-L1-dependent cancer cell proliferation, and targeting this signaling pathway in NSCLC could be interesting due to EGFR overexpression, which is highly associated with many NSCLC cells, including A549 and H460." (PMID 37998363, 2023). "The chronic activation of EGFR may lead to oncogenic dependence on the EGFR signaling pathway, thereby sensitizing cancer cells to EGFR TKIs such as gefitinib." (PMID 37834377, 2023). "Interestingly, several multi-omics analyses prove that MAPK3 occupies one of the top networking protein positions along with EGFR in various cancers, resulting in poor prognosis." (PMID 38067326, 2023). "Importantly, CD47‐SIRPα blockade with an anti‐CD47 antibody treatment significantly enhances EGFR‐targeted cancer therapy." (PMID 37541303, 2023). "Therefore, targeted therapy targeting the EGFR signaling has become the focus of drug development for cancer treatment." (PMID 37944197, 2023). "Together, these data indicate that targeting retrotranslocation of EGFR may be a potent therapeutic for RTK-active cancer." (PMID 36253541, 2023). "The N-glycosylation difference at this site between these paired HCT116 cancer cells and DKO1 non-tumorigenic cells suggests the N-glycosylation at N175 may be used as a cancer biomarker or may contribute to EGFR as an oncogenic driver." (PMID 36639722, 2023). "Highlighting this, Alexander and Burbury determined that studies describing an increased risk of VTE with EGFR expression often do not provide a timeline for their thrombotic complications relative to the cancer diagnosis and treatment." (PMID 37232831, 2023). "Safety, toxicity profiles, and target cancers of EGFR inhibitors." (PMID 37601068, 2023). "Interestingly, CH223191 exerts synergistic anti-cancer effects with erlotinib, an EGFR inhibitor, in BT20, MDA-MB-468, and HCC1937 cells." (PMID 37241719, 2023). "EMT is required for cancer metastasis, and has closely relationship with EGFR inhibitor resistance." (PMID 36841821, 2023). "EGFR testing in NSCLC is known to be essential for identifying targetable mutations and ensuring all patients are receiving the most appropriate treatment for their cancer type." (PMID 37713929, 2023). "Furthermore, the significant EGFR inhibitory activity of pyridazine-pyrazoline candidate IV explained its noticeable antiproliferative activity against breast T-47D and renal UO-31 cancer cell lines." (PMID 37959672, 2023). "Therefore, it is important to understand the factors that are responsible for the overactivation of EGFR in cancer." (PMID 37834119, 2023). "We propose that if an EGFR inhibitor with gold nanoparticles on its surface is attached to cancer cells, the radiosensitizing effect of the EGFR inhibitor may be enhanced." (PMID 38067400, 2023). "CD27xEGFR’s FcR independence, relying on EGFR+ cancer cells to provide a CD27 cross-linking platform, could avoid these unwanted effects." (PMID 37545491, 2023). "Surprisingly in this malignant tumor, EGFR mRNA is downregulated compared to NIFTP and FND." (PMID 37114127, 2023). "In previous studies, Lrig1 has been known to be involved in EGFR degradation in cancer cells." (PMID 37666819, 2023). "On the other hand, the decreased expression of EGFR (epidermal growth factor receptor), which takes part in the regulation of cell growth, proliferation, differentiation, and survival, could be one of the important targets in cancer therapy." (PMID 37834191, 2023).
cancer (continued). "Small molecule inhibitors of NONO and other LLPS-associated proteins could be a potent therapeutic strategy for inhibiting the activation of the EGFR pathway and sensitizing cancer cells to conventional therapies." (PMID 37580790, 2023). "Accordingly, a low affinity EGFR ADC (RN765C), showed potent killing of moderate to high EGFR-expressing cancer cell lines yet showed limited toxicity to human epidermal keratinocytes, and was effective as a single-dose treatment in a pancreatic xenograft model." (PMID 37880707, 2023). "Additionally, publicly available cytotoxicity data confirmed the synergistic effect of EGFR inhibitors in combination with daunorubicin in all 60 investigated cancer cell lines." (PMID 37629110, 2023). "It is hypothesized that these EGFR-TKI DTCs are an important source of cancer cells that will acquire resistant mechanisms to EGFR-TKIs." (PMID 36831438, 2023). "EGFR is highly expressed in some cancers, and EGFR inhibitors are used to block cancer cell growth." (PMID 36973040, 2023). "The multifunctional delivery vector decorated by AS1411 conjugated hyaluronic acid and NLS‐GE11 peptide conjugated hyaluronic acid can specifically target circulating malignant cells (CMCs) of cancer patients to deliver the genome editing plasmid for epidermal growth factor receptor (EGFR) knockout." (PMID 37590231, 2023). "EGFR homodimers unaided may lead to cancer, but EGFR2 does form heterodimers, resulting in malignancy." (PMID 38090376, 2023). "The use of EGFR-TK inhibitory action revolutionizes cancer treatment." (PMID 36768973, 2023). "However, EGFR mutations can lead to increased auto-phosphorylation and MAPK signalling in some cancers (e.g., NSCLC), displaying abnormal ubiquitination and an increased rate of internalization and recycling." (PMID 37296932, 2023). "Targeting the KID pro-survival function of EGFR by lowering its protein level may be helpful in finding more effective ways of targeting EGFR for cancer therapy." (PMID 37446288, 2023). "Thus, the overexpression of EGFR has been observed in many human cancers, such as bladder, breast, colon and lung cancers." (PMID 36043746, 2023). "Thus, we conducted a prospective study to evaluate the efficacy of both tissue NGS (tissue rebiopsy) and liquid NGS (liquid rebiopsy) at the time of cancer progression after first‐line EGFR‐TKI treatment in patients with advanced NSCLC." (PMID 38140788, 2023). "By being active at the level of EGFR lysosomal degradation, CucB may effectively target cancer cells bearing either wild-type or mutant EGFR." (PMID 38001865, 2023). "As epidermal growth factor receptor (EGFR), Vav1, RhoA, Rac1, and BPGAP1 are all associated with cancer metastasis, BPGAP1 could provide a crucial checkpoint for the EGFR-BPGAP1-Vav1-Rac1-RhoA signaling axis for cancer intervention." (PMID 36598812, 2023). "EGFR, HER2, and ERBB3 are all related to the causation and progression of cancer." (PMID 35822637, 2023). "This work paves the way that the TGFaL3-Peptide conjugates produced in this work could be used for targeting the treatment of EGFR-expressing cancer cells, and will build the ground for in vivo investigations of these novel conjugates." (PMID 37445686, 2023). "The epidermal growth factor receptor (EGFR) is vital for many different types of cancer." (PMID 37623652, 2023). "However, cancer cells can maintain cell proliferation by activating alternative signaling pathways, such as EGFR/ErbB and PI3K/Akt/mTOR, to resist sorafenib-induced apoptosis." (PMID 37296859, 2023). "After highlighting the ability of GBM-EVs to induce the release of EGFR and phospho-EGFR, the authors also reported similar findings in additional cancer cell lines, including A431 (epidermal), MDA-MB-231 (breast), BxPC3, PANC-1 (pancreatic), PC-3 (prostate), HCT116, DLD-1, and CaCo-2 (colon)." (PMID 37296932, 2023).
cancer (continued). "The resistance of cancer cells to molecularly targeted therapies, promotion of the epithelial-mesenchymal transition (EMT), and increased invasion of cancer cells are all caused by the crosstalk between Notch and EGFR signalling." (PMID 37441599, 2023). "EGFR is implicated as a driver of cancer progression, and EGFR inhibitors are approved for use in non-small cell lung, colorectal and gastric cancers." (PMID 36138170, 2023). "Among them, the main gene-rich pathways include Endocrine resistance, Nitrogen metabolism, EGFR tyrosine kinase inhibitor resistance, Pathways in cancer, Steroid hormone biosynthesis and so on, and we found that these signal pathways are closely connected with PI3K/Akt." (PMID 37533633, 2023). "EGFR has been identified as a biomolecular target for cancer since its discovery." (PMID 36768973, 2023). "Since EGF can bind to receptors other than EGFR, such as ErbB2 (HER2), ErbB3 (HER3), and ErbB4 (HER4) across most cancer contexts, and is a key player in cancer metastasis, it is likely that the EGF-associated mechanisms driving EMT are distinct from those regulating MHC I expression." (PMID 38067396, 2023). "The incubation of cancer cells for more than two hours with FQTT derivatives leads to the significant degradation of the EGFR, which is accompanied by a decrease in the content of cytoskeletal proteins β-actin and α-tubulin, commonly used as load controls in Western blotting." (PMID 37754201, 2023). "In addition to delivery of conventional anti-cancer drugs, nanoparticles can also be used to deliver non-coding RNAs (ncRNAs) to tackle EGFR-TKI resistance." (PMID 36910653, 2023). "EGFR plays a key role in angiogenesis and cancer cell growth." (PMID 36676140, 2023). "Moreover, a recent study showed that pharmacological targeting of PARP led to enhanced sensitivity of cancer cells to EGFR inhibition." (PMID 37441599, 2023). "In conclusion, we reported on molecular characteristics of EGFR‐LFD in Asian pan‐cancer patients." (PMID 36622089, 2023). "Furthermore, polymeric micelles based on benzyl-poly(ε-caprolactone)-b-poly (ethylene glycol) encapsulating a photosensitizer temoporfin and an EGFR-targeted nanobody, EGa1, were shown to enhance nanobody uptake and increased phototoxicity towards cancers." (PMID 38067344, 2023). "Thus, the combination therapy of theasinensin A with nimotuzumab is a powerful candidate for treatment of wild-type EGFR cancers." (PMID 37762316, 2023). "We postulate that these observations may provide novel opportunities for therapeutic interventions for EGFR driven cancers." (PMID 37399454, 2023). "This review highlights the functional roles of EGFR and EGFR TKIs in cancer and AD." (PMID 37601068, 2023). "The activation of the EGFR/PI3K/AKT/mTOR pathway has been observed in various cancer types." (PMID 37631344, 2023). "One of the most frequently studied and used RTKs in the battle against cancer is EGFR." (PMID 37446288, 2023). "EGFR, as a molecular target, has crucial role in cancer treatment." (PMID 37670360, 2023). "Several genes [e.g., epidermal growth factor receptor (EGFR) and amyloid precursor protein (APP)] are associated with both cancer and AD, and we and others have recently found that anti-cancer drugs can penetrate the blood-brain barrier (BBB) and modulate AD pathology." (PMID 37601068, 2023). "The EGFR signaling cascade is a key regulator in cell proliferation and cancer development." (PMID 36043445, 2023). "In addition, EGFR-TKI treatment is reported to induce reactive oxygen species (ROS) in cancer cells, which in turn, can induce PAI-1 expression." (PMID 36831438, 2023).
cancer (continued). "Studies have proven the role of EGFR in the pathogenesis and progression of various cancers." (PMID 37042307, 2023). "For example, the well-known ubiquitin E3 ligase C-CBL could mediate the neddylation of EGFR, TβRII, and c-Src in different cancer cells." (PMID 36834826, 2023). "In this report, we showed for the first time that CBX3 gene amplification strongly co-occurs with both EGFR and RAC1 genes in different human cancers and that this molecular event is associated with an increase of mRNA and protein levels of CBX3, EGFR and RAC1." (PMID 37633946, 2023). "AREG may interact with epidermal growth factor receptor (EGFR) to promote the growth of cancer cells." (PMID 37197416, 2023). "Nevertheless, antibody‐based therapy of cancer has achieved significant success in the last years and MABs against EGFR (cetuximab, panitumumab), ERBB2 (trastuzumab, pertuzumab), and ERBB3 (patritumab, seribantumab, lumretuzumab) are used to treat various type of cancer." (PMID 37341059, 2023). "It is well known that activation of KRAS is regulated by EGFR signaling in cancer cells." (PMID 37649607, 2023). "Next, we set out to check whether the co-amplification of CBX3 with either EGFR or RAC1 genes might affect cancer aggressiveness and patient lifespan." (PMID 37633946, 2023). "Targeting both EGFR and PI3K signaling pathways may be useful for optimal therapeutic activity in cancer to prevent or overcome EGFR-tyrosine kinase resistance and/or activation of compensatory pathways." (PMID 38033496, 2023). "This study demonstrates that AuNP-NmAb has a great potential for the treatment of EGFR+ cancers." (PMID 37623652, 2023). "Endocytosis is a key mechanism for internalizing cell surface molecules and surface-bound cargos, and more importantly, trafficking of intrinsic or stress-induced EGFR vesicle from endocytosis has been reported as an alternative mechanism rendering cancer cell drug resistance." (PMID 37495186, 2023). "Moreover, the UBE2M and c-Cbl axis have been shown to promote the neddylation of the EGFR, leading to its sorting and degradation, which prevents the overactivation of EGFR in cancer cells." (PMID 37717015, 2023). "Numerous cancer types express lower survival rates when EGFR is expressed." (PMID 36893122, 2023). "In vitro: PCZ exhibits a synergistic effect on cancer cell death, both in vitro and in xenograft models, and improves the overall survival of mice.In vivo: alters EGFR distribution, reversibly inhibit the endocytosis of membrane proteins targeted by therapeutic monoclonal antibodies." (PMID 38074670, 2023). "In addition, many reports have indicated that 6-shogaol induces apoptotic cell death by inhibiting the phosphorylation of EGFR in various cancer cell types." (PMID 36768961, 2023). "Preclinical and early clinical trials on EGFR inhibitors, including erlotinib, have shown that these inhibitors are well tolerated and may be beneficial for patients with various cancers." (PMID 37863665, 2023). "This hypothesis finds support in the detection of serum IgG antibody attachment to OMVs through ELISA assay, as well as, the specific binding of scFv-OMVs to diverse EGFR-overexpressed cancer cells." (PMID 37775519, 2023). "Our study reveals the intricate interplay between AXL, MIG6 and EGFR signaling in cancer." (PMID 37834326, 2023). "In addition, they were also involved in many critical cancer-related pathways, including EGFR, TGF-β, and PI3K/AKT signaling pathways." (PMID 37007025, 2023). "Additional levels of complexity are related to non-canonical mechanisms of EGFR signaling, such as those associated with its nuclear translocation or with the recently reported release of EGFR-containing exosomes from cancer cells." (PMID 36817764, 2023).
cancer (continued). "Many ATP-competitive EGFR/HER2 RTK (receptor tyrosine kinase) dual small molecule inhibitors bearing diverse chemical scaffolds are widely tested in human clinical studies for cancer therapy." (PMID 37096560, 2023). "Here, we demonstrated that statin could also upregulate CD55 expression on hMSCs and that erlotinib, an FDA-approved EGFR inhibitor for the treatment of cancer, was able to increase CD55 expression on hMSCs." (PMID 37357314, 2023). "Moreover, Gong and coworkers synthesized anti–EGFR nanobody 7D12 for cancer cell targeting as an alternative genetic approach method." (PMID 37344853, 2023). "AXL could be transactivated by EGFR in cetuximab–resistant cells and may serve as a potent target in advanced cancer therapy." (PMID 37834326, 2023). "It should be noted that acquired clinical resistance to EGFR inhibitors in cancer is usually the result of a tertiary mutation combining the C797S mutation, MET amplification, and KRAS mutations, among which the C797S mutation in the EGFR is the dominant one." (PMID 37754201, 2023). "Since the amino thiazole derivatives have shown potent EGFR kinase inhibition property, the compounds containing this moiety could be potential EGFR inhibitors for anti-cancer therapy." (PMID 37298747, 2023). "Identifying modifier genes of the EGFR expression/pathway could improve therapeutic treatments for this aggressive cancer type." (PMID 36675308, 2023). "Moreover, the co-regulation of both HER-2 and EGFR has been reported to fuel the progression and severity of different cancers." (PMID 37108498, 2023). "This study may provide new insights into the EGFR regulatory network and may help to advance cancer treatment." (PMID 37834326, 2023). "Targeting EGFR and its inhibition can prevent cancer growth by inducing apoptosis." (PMID 38034159, 2023). "Mechanistic studies demonstrated that high CYP2J2 expression strongly enhanced proliferation and reduced apoptosis in several cancers via the activation of kinase/Akt signaling pathways and increased the phosphorylation of epidermal growth factor receptor (EGFR)." (PMID 38001897, 2023). "In addition to gene amplification and the epigenetic upregulation of the EGFR gene, changes in positive or negative regulators of EGFR can also affect its abundance in cancer cells." (PMID 37631344, 2023). "Epidermal Growth Factor Receptor (EGFR) is a major driver of cancer." (PMID 37296932, 2023). "Although it will be important in future studies to assess the precise underlying mechanisms by which TRPV1 regulates autophagy-dependent EGFR activation, this connection immediately hints at several potentially promising therapeutic targets to control cisplatin-resistant cancer in the clinic." (PMID 37165076, 2023). "In addition, it is important to outline that the link between PGE2 and EGFR was also observed in cellular and in vivo models of cancers where endogenous PGE2 production is abrogated by COX2 or mPGES1 inhibition." (PMID 37190301, 2023). "we found that combination of PELI1 knockdown and EGFR inhibition significantly decreased metastatic potential of cancer cells to lung in caudal vein xenograft models compared to the either single treatment, as demonstrated by reduced number of micrometastatic nodules." (PMID 36841821, 2023). "Through the PI3K-Akt, HIF-1, and ErbB signaling pathways, curcuma regulates key targets that are involved in angiogenesis, cancer cell proliferation, metastasis, invasion, and chemotherapy resistance, including AKT1, TNF, STAT3, EGFR and HSP90AA1, in the treatment of OS." (PMID 37311820, 2023). "A total of 14,260 subjects were excluded due to absence of mNSCLC cancer, absence of systemic treatment received, or presence of EGFR mutation or ALK translocation." (PMID 37311845, 2023).